SP1 (Sp1 transcription factor)
Diseases named in the same sentence as SP1 in open-access papers (continued):
Sharing a sentence is not in itself a finding about the gene and the disease.
cervical cancer (34 papers, 2012 to 2025). A primary or metastatic malignant neoplasm involving the cervix. "In summary, the findings indicated that the functional XRCC1 SNP rs3213245 was associated with the risk of cervical cancer based on the Sp1/Krox-20 switch." (PMID 29156789, 2017). "Finally, the underlying mechanisms and effects of Sp1 on the mitochondrial network and metabolism of cervical cancer were analysed both in vitro and in vivo." (PMID 37147632, 2023). "In cervical cancer, SP1 has been shown to contribute to radioresistance through inhibiting G2/M phase arrest by targeting CDK1." (PMID 39800760, 2025). "Cdk1 is known as a transcriptional target of E2F1 and Sp1 proteins which is responsible for G1/S progression, and its overexpression has been stated in cervical cancer." (PMID 41516135, 2025). "In the end, our work showed that HDAC1 overexpression, via a unique Sp1/PP2A/pRb pathway, reduced proliferation and caused cervical cancer cells to undergo premature senescence." (PMID 40171441, 2025). "In vivo studies further demonstrated that the progression of cervical cancer was positively correlated with Sp1 levels." (PMID 37147632, 2023). "In the present study, we detected Sp1 expression in different types of cervical cancer and assessed the effect of Sp1 on tumour progression." (PMID 37147632, 2023). "Taken together, these data indicated that the activity of aerobic glycolysis was positively regulated by Sp1 in cervical cancer cells." (PMID 37147632, 2023). "The effect of Sp1 expression on the biological characteristics of cervical cancer cells was assessed by colony, wound healing, transwell formation, EdU, and TUNEL assays." (PMID 37147632, 2023). "We suggest that Sp1-mediated mitochondrial network remodelling and glucose metabolism reprogramming are pivotal in cervical cancer progression and can be targeted for cervical carcinoma therapy." (PMID 37147632, 2023). "Previous studies have shown that Sp1 is overexpressed in multiple types of cancers, including cervical cancer." (PMID 37147632, 2023). "Altogether, these data suggest that Sp1 positively regulates the biological behaviour of cervical cancer cells." (PMID 37147632, 2023). "Collectively, these data indicated that Sp1 promoted mitochondrial morphology remodelling by regulating both mitofusin and mitofission in cervical cancer cells." (PMID 37147632, 2023). "Desferal (deferoxamine) controls the expression of human copper transporter 1 and transferrin receptor 1 via Sp1, and it exhibited synergistic cytotoxicity in combination with oxaliplatin in human cervical cancer cells." (PMID 35550011, 2022). "For instance, miR-296 relative expression level decreased in cervical cancer tissues and cell lines, and can directly targets specificity protein 1 (SP1) to suppress cell proliferation and invasion." (PMID 33028966, 2020). "We identified that TIP60-mediated growth suppression of HPV-induced cervical cancer is mediated in part due to TERT repression through Sp1 acetylation." (PMID 29045464, 2017). "In conclusion, we have shown that the transcription factor Krox-20 was recruited to the XRCC1 rs3213245 mutation region and regulated the transcription of the XRCC1 gene by interacting with Sp1, ultimately mediated cervical cancer development." (PMID 29156789, 2017). "Interferon-β dependent induction of hsa-miR-129-5p in cervical cancer cells was shown to reduce E6 and E7 expression via targeting of SP1." (PMID 27270309, 2016). "The dominant negative mutant of Sp1 demonstrated a growth inhibitory effect in cervical cancer cell lines." (PMID 23403540, 2013). "In addition, RNA sequencing data showed that Sp1 expression was positively correlated with the expression of Mfn1/2, Opa1, and Drp1 in tissues of cervical cancer patients." (PMID 37147632, 2023). "In the present study, we investigated whether Sp1 could affect mitochondrial morphology in cervical cancer cells." (PMID 37147632, 2023).
cervical cancer (continued). "Importantly, there was a strong upregulation of Ki-67 in the Sp1-OE group but was decreased in the Sp1-KD nude mouse group, suggesting that cervical cancer cell proliferation was positively regulated by Sp1." (PMID 37147632, 2023). "In vivo data confirmed that Sp1 negatively regulated cell apoptosis in cervical cancer." (PMID 37147632, 2023). "To investigate whether Sp1 could affect mitochondrial morphological remodelling in cervical cancer cells, we analysed the morphological characteristics of mitochondria using microP." (PMID 37147632, 2023). "Additionally, the Sp1-mediated reprogramming of glucose metabolism played a critical role in the progression of cervical cancer cells." (PMID 37147632, 2023). "Despite the potential link between Sp1 and mitochondrial dynamics, the intrinsic regulatory relationships among Sp1, mitochondrial dynamics, and metabolic reprogramming in cervical cancer cells remain unclear." (PMID 37147632, 2023). "Moreover, ChIP/Re-ChIP assays revealed that transcription factor Krox-20 was recruited to the XRCC1 rs3213245 mutation region and regulated the transcription of the XRCC1 gene by interacting with Sp1, ultimately mediated cervical cancer development." (PMID 29156789, 2017). "In addition, the XRCC1 mRNA level of cervical cancer patients was determined to verify the transcriptional regulation of XRCC1 by the Sp1-Krox-20 complex in vivo." (PMID 29156789, 2017). "We next investigated whether Sp1 could affect cervical cancer cell migration." (PMID 37147632, 2023). "In summary, these data strongly implied that Sp1 might suppress apoptosis in cervical cancer cells." (PMID 37147632, 2023). "Targeting Sp1 could be an effective strategy for the treatment of cervical cancer." (PMID 37147632, 2023). "Thus, we suggest that Sp1 might regulate cervical tumorigenesis by regulating aerobic glycolysis in cervical cancer cells." (PMID 37147632, 2023). "Beyond these genes, miRNAs also play a crucial role in regulating transcription factors such as SP1 and MYC, which are pivotal drivers of cervical cancer progression." (PMID 40817807, 2025). "We show that TAZ is specifically upregulated by HPV18 E7 in an SP1-dependent manner and plays an oncogenic role in HPV18+ cervical cancer cell lines." (PMID 38987584, 2024). "Sp1 knockdown increased kallikrein-10 (KLK10) expression, indicating that the miR-7/Sp1 axis acts as a key regulator of MTA2, affecting both KLK10 expression and mobility in cervical cancer cells." (PMID 38632598, 2024). "The human specificity protein 1 (SP1) transcription factor belongs to the C2H2-type zinc finger family, and has been widely studied in HeLa cells (human cervical cancer cells)." (PMID 37046316, 2023). "By analyzing the differential expression of CXC chemokines in cervical cancer, we identified three key transcription factors (RELA, NFKB1 and SP1)." (PMID 34321012, 2021). "It has also been demonstrated that a specific Sp1 recognition sequence is critical for the transactivation of the TGF-β1 promoter by HPV16 E6 and E7 in cervical cancer." (PMID 25619363, 2015). "Taken together, our results suggest that the induced expression of miR-129-5p by IFN-β suppress the progression of cervical cancer by down-regulating HPV-18 E6 and E7 expression, and SP1 is a direct downstream target of miR-129-5p." (PMID 24358111, 2013).
cervical cancer (continued). "Leveraging miRNAs to concurrently target transcription factors such as SP1 and MYC may provide synergistic therapeutic benefits, paving the way for innovative combination strategies that exploit the vulnerabilities of cervical cancer." (PMID 40817807, 2025). "Because SP1 acetylation inhibits TERT, cervical cancer growth is inhibited." (PMID 34130593, 2021). "MMA has been shown to inhibit Sp1 binding to other genes with GC rich promoter motifs, and Sp1 expression is also inhibited by MMA in a number of cell types, such as cervical cancer KB cell lines, human gastric cancer N87cell lines, primary neuronal cells and prostate cancer PC3 and LNCaP cells." (PMID 27695039, 2016). "In non-quenching mode, we found that MMP was decreased by Sp1 knockdown in cervical cancer cells." (PMID 37147632, 2023). "In addition, PEITC treatments attenuated the transcription factor Sp1 and its downstream target, a drug efflux transporter protein P-gp, which further supports a potential role for PEITC in targeting therapy-resistant CSCs in the context of cervical cancer." (PMID 30818757, 2019).
diabetes (29 papers, 2011 to 2025). "Reduced SP1 protein levels in the setting of inflammation and diabetes have been previously implicated in decreased eNOS transcription." (PMID 34026871, 2021). "Likewise deregulation of Sp1 via the abundance or its posttranslational modification is well known to at least in part cause diabetes." (PMID 25054881, 2014). "In diabetes, alterations in SP1-related pathways are considered one of the important reasons for disease development." (PMID 41372957, 2025). "Regarding AGE accumulation in diabetes, we found that AGEs induce the activation of transcription factors NF-κB and specificity protein 1 (SP1) in retinal neurons." (PMID 37298118, 2023). "Silencing of SP1 enhanced the M1 polarization of macrophages in murine lung tissues of Type 2 diabetes mellitus." (PMID 37744330, 2023). "Our previous study showed diabetes aggravates CRC by increasing specificity protein 1 (Sp1) expression." (PMID 29530061, 2018). "Decreased Sp1 expression was found previously in vascular endothelial cells incubated in high glucose concentration in vitro and diabetes in vivo." (PMID 23285265, 2012). "The diabetes-responsive SP1-targeting genes in different kidney cells remain to be elucidated." (PMID 38467599, 2024). "E2f1, Sox10 and SP1 were found to likely regulate the expression of genes found only in diabetes." (PMID 38039846, 2024). "However, there is less evidence investigating the relationship between SP1 and diabetes or cardiovascular diseases." (PMID 36675183, 2023). "During diabetes, inhibition of miR-22-3p increases claudin-1 and -3 expression by directly targeting Sp1, resulting in lower epithelial paracellular permeability in SMG epithelial cells, which might contribute to the dysfunction of the diabetic SMG." (PMID 34831451, 2021). "4EBP1 was also positively associated with genes coupled to diabetes pathways, genes regulated by the transcription factors E2F, USF and SP1, the oncogenes HRAS and HOXB13 and several genes involved in negative regulation of translational initiation (EIF4EBP2, EIF2B3, EIF2C2)." (PMID 26698305, 2015). "O-glycosylation can modify protein-protein interaction; therefore, O-glycosylation of Sp1 may change its interaction with other proteins of the transcription machinery in such a manner that it favors the expression of diabetes related genes." (PMID 23554695, 2011). "Since DCs are a rapid-onset and frequent complication of diabetes mellitus, the authors attempted to define whether β-CM-7 could exert antioxidant protection through the modulation of transcription factors such as FoxO1 and Sp1, known regulators of oxidative stress responses." (PMID 40507153, 2025). "A comprehensive transcriptomic analysis involving type 2 diabetes mellitus patients further revealed that miR-124-3p and miR-16-5p affect the expression of genes such as CREB1, SP1, (both TFs in our analysis) SREBF1, and JUN (hub genes)." (PMID 36232337, 2022). "TF prediction analysis showed that NR3C1, TEAD and TFs that cooperate with YAP-TEAD, such as Klf4, SP1, AP1, MYC and ZEB1, were enriched in the DEGs of the diabetes vs. control comparison." (PMID 34970541, 2021). "Finally, a recent study from Abel and colleagues noted that that restoring glucose delivery to cardiomyocytes in the context of streptozotocin-induced diabetes could result in acceleration of mitochondrial dysfunction, an effect mediated by elevated O-GlcNAcylation of the transcription factor Sp1." (PMID 34113491, 2021). "Western blotting showed high levels of HIF‐1α, SP1 and ROBO4 after 4 weeks of uncontrolled diabetes, with levels sustained at 6 and 8 weeks." (PMID 31094072, 2019). "For example, in the amelioration of diabetes, miR-129-3p decreases the apoptosis and recruitment of neutrophils by regulating the translation of Casp6 and Ccr2, whereas miR-129-5p inhibits ECM degradation by inhibiting the expression of Sp1-mediated MMP9." (PMID 34777000, 2021).
diabetes (continued). "Our findings implied miR-199a could be a therapeutic target by regulating SP1 directly to affect EMT in diabetic cataract and provided novel insights into the pathogenesis of diabetic cataract." (PMID 33276722, 2020).
Hyperglycemia (27 papers, 2012 to 2026). An increased concentration of glucose in the blood. "To understand the transcriptional signature of hyperglycemia-responsive dynein genes underlying early podocyte injury, we identified SP1 as the most likely TF because it binds to the most common motifs in the promoters of all these dynein genes." (PMID 38467599, 2024). "The mechanism of decreased expression of the thiamine transporters in hPTECs in model hyperglycemia is unknown may be linked to transcription factor Sp1." (PMID 23285265, 2012). "Through promoter analysis, we identified binding sites for transcription factor specificity protein 1 (SP1) as the most shared motif among hyperglycemia-responsive dynein genes." (PMID 38467599, 2024). "The direct repression of AMPK, an energy sensor, replicates hyperglycemia-induced dynein expression by activating SP1." (PMID 38467599, 2024). "Inhibition of the SP1/ROBO4 pathway significantly ameliorated hyperglycemia-induced HRECs dysfunction." (PMID 37430272, 2023). "It was demonstrated that the heightened production of mitochondrial superoxide due to hyperglycemia leads to an elevation in hexosamine synthesis and the O-glycosylation of specificity protein 1 (Sp1)." (PMID 38068400, 2023). "Hyperglycemia has been shown to increase the degree of SP1 modification with O-GlcNAc through the hexosamine biosynthesis pathway (HBP)." (PMID 36849424, 2023). "A number of studies have reported that the transcription factor Sp-1 mediates hyperglycemia-induced upregulation of various genes, thus contributing to high glucose-induced endothelial injury 30-32." (PMID 33754057, 2021). "Here, we assessed the roles of miR‐125b‐5p and miR‐146a‐5p in HIF‐1α/SP1‐mediated ROBO4 expression in vivo in diabetic rats or in vitro in RPE cells under hyperglycaemia or hypoxia." (PMID 31094072, 2019). "Over increasing durations of hyperglycemia exposure, SP1 mRNA levels were evaluated in HRECs and ARPE-19 cells after normalization relative to the mRNA levels of Pumilio homolog 1 (PUM1) and peptidylprolyl isomerase A (PPIA), respectively." (PMID 28706953, 2017). "Subsequently, we transfected an miR-125b-5p mimic into ARPE-19 cells under hyperglycemia exposure, confirmed miR-125b upregulation, and determined the SP1-expression level at both the mRNA and protein levels." (PMID 28706953, 2017). "Accordingly, in ARPE-19 cells, miR-125b upregulation abolished the high levels of SP1 induced by hyperglycemia." (PMID 28706953, 2017). "In both cultured podocytes and the STZ-induced type 1 diabetes mouse model with hyperglycemia as the major pathologic factor, we demonstrated activation of SP1 transcription activity and subsequent increased expression of the hyperglycemia-responsive dynein subunits." (PMID 38467599, 2024). "Previous studies have indicated that SP1 is involved in hyperglycemia-mediated endothelial injury." (PMID 35607962, 2022). "Thus, inhibition of SP1/ROBO4 under hyperglycaemia or HIF‐1α/ROBO4 under hypoxia reduced cell motility." (PMID 31094072, 2019). "Moreover, this transfection reduced hyperglycaemia‐induced SP1 and ROBO4 up‐regulation at both mRNA and protein levels." (PMID 31094072, 2019). "Modification of SP1 through N-acetylglucosamine may explain the relationship between activation of the hexosamine pathway and hyperglycemia." (PMID 29937497, 2018). "However, the mechanism by which hyperglycemia induces the SP1-mediated transcription of dynein genes is unknown." (PMID 38467599, 2024). "However, under hyperglycaemia, SP1 siRNA, ROBO4 siRNA and miR‐125b‐5p could protect against HG‐stimulated RPE migration, and HIF‐1α siRNA, ROBO4 siRNA and miR‐146a‐5p could also prevent hypoxia‐induced RPE migration." (PMID 31094072, 2019). "Hyperglycemia and hyperinsulinemia upregulate cardiomyocyte SGLT1 by activating ERK, the transcription factors HNF-1 and Sp1, and the transcript stabilizer HuR." (PMID 40932483, 2025).